UBE2C (ubiquitin conjugating enzyme E2 C)
Diseases named in the same sentence as UBE2C in open-access papers (continued):
Sharing a sentence is not in itself a finding about the gene and the disease.
breast carcinoma (continued). "However, we previously showed that high UBE2C mRNA expression is significantly associated with poor DFS, DMFS, and OS only in patients with HR+/HER2– breast cancer among the four subtypes." (PMID 32039034, 2019). "HR+/HER2– breast cancer cell lines expressed the UBE2C protein at detectable levels." (PMID 32039034, 2019). "Therefore, we suggest that the combination of palbociclib with tamoxifen is a promising treatment strategy in patients with HR+/HER2– breast cancer overexpressing UBE2C." (PMID 32039034, 2019). "Univariate and multivariate analyses showed that high UBE2C expression was associated with significantly shorter survival of breast cancer patients with pN0 and pN1 tumors but not pN2/N3 tumors (P < 0.05)." (PMID 32039034, 2019). "Many studies report that high UBE2C expression is associated with poor survival in patients with breast cancer irrespective of subtype." (PMID 32039034, 2019). "However, this study analyzed the association between UBE2C expression and clinical outcomes only in HR+/HER2– breast cancer through a parametric survival analysis using public datasets and a patient cohort." (PMID 32039034, 2019). "This may explain why high UBE2C expression was strongly associated with poor DMFS, DFS, and OS only in patients with HR+/HER2– breast cancer." (PMID 32039034, 2019). "Overexpressed UBE2C is related to worse survival of patients with breast cancer, indicating that UBE2C may play an oncogenic role in the progression of the disease." (PMID 29685151, 2018). "Ubiquitin-conjugating enzyme E2C (UBE2C) has been previously reported to correlate with the malignant progression of various human cancers, however, the exact molecular function of UBE2C in breast carcinoma (BRCA) remained elusive." (PMID 29021715, 2017). "In addition, cells with UBE2C knockdown sensitized breast cancer cells to radiation, doxorucibin and the hormone-blocking agents tamoxifen and letrozole." (PMID 24699941, 2014). "Because we found that UBE2C induction might play a role in breast lesions, although the link with malignant tumor progression was ambiguous, we investigated the carcinogenic role of UBE2C in the human breast cancer cell lines MCF-7 and MDA-MB-231." (PMID 24699941, 2014). "UBE2C expression was associated with that of the selected metastasis-related genes VEGF, CXCL-4, CCL5, NEDD9 and RHoC, in MCF-7 cells, so UBE2C may be involved in breast cancer metastasis." (PMID 24699941, 2014). "In this study, we evaluated whether UBE2C could be a tumor marker of early breast cancer with MC found on screening mammography." (PMID 24699941, 2014). "FOXA1, ESR1 and UBE2C, are known as breast cancer prognosis biomarkers." (PMID 21806811, 2011). "Furthermore, expression levels are higher in metastases of breast cancer tumors (p < 0.001 and p < 0.01, for UBE2C and AURKA respectively), which again points to a role for these proteins in metastatic behavior." (PMID 20630075, 2010). "We confirmed that UBE2C protein measured by IHC could be used as a prognostic marker in N+ breast cancer." (PMID 19513072, 2009). "Interestingly, the inhibition of UBE2C could also induce senescence in breast cancer cells, which was first reported by our group." (PMID 40729680, 2025). "Moreover, UBE2C knockdown promoted the ubiquitination of TOP2A in breast cancer cells." (PMID 40729680, 2025). "However, UBE2C knockdown sensitized breast cancer tumors to doxorubicin." (PMID 40729680, 2025). "Thus, we hypothesized that UBE2C knockdown sensitized breast cancer cells to doxorubicin through the synergistic inhibition of TOP2A." (PMID 40729680, 2025). "Moreover, UBE2C knockdown reduced the protein stability of TOP2A in breast cancer cells." (PMID 40729680, 2025).
breast carcinoma (continued). "Moreover, the gene methylation of KIF2C was significantly elevated in luminal A breast cancer samples with prognostic value, together with three other cell cycle and proliferation regulators Ki-67, UBE2C (ubiquitin conjugating enzyme E2C) and HDAC4 (histone deacetylase 4)." (PMID 38344808, 2024). "The top four upregulated differentially expressed genes (DEGs), SAA2, UBE2C, CEMIP and ANXA8L1, have been associated with increased inflammation, cancer progression, metastatic potential and overall poor survival outcomes of various cancers including breast cancer." (PMID 39768151, 2024). "As important members of the E2 family, it was reported that UBE2S and UBE2C were highly expressed in cancerous tissues compared with surrounding normal tissues, and aberrant expression of the genes was reported to be involved in tumorigenesis and tumor progression, including breast cancer." (PMID 36860312, 2023). "Therefore, we propose that combining UBE2S or UBE2C with Numb may serve as an effective predictor of breast cancer survival." (PMID 36860312, 2023). "In addition, we found that overexpression of UBE2S or UBE2C led to increased capabilities of colony formation and cell proliferation while silencing of UBE2S or UBE2C displayed opposite trends in breast cancer cells, indicating the tumor-promoting effect of elevated UBE2S or UBE2C expression." (PMID 36860312, 2023). "In contrast, UBE2C is highly expressed in lung cancer, esophageal adenocarcinomas, liver cancer, nasopharyngeal carcinoma, and breast cancer, demonstrating that UBE2C may be involved in carcinogenesis and play an essential role in tumorigenesis and cancer progression." (PMID 38102624, 2023). "UBE2C may also be a therapeutic target in breast cancer and ovarian cancer." (PMID 36293188, 2022). "However, the clinical and functional significance of UBE2C expression in HR+/HER2– breast cancer remains unknown." (PMID 32039034, 2019). "Additionally, it is worth mentioning that our data pointed out a positive correlation between the expression of both genes, as well as of FOXM1 protein and UBE2C gene expression, and also demonstrated that FOXM1 binds onto UBE2C promoter in a breast cancer cell line." (PMID 29596365, 2018). "Moreover, the result that UBE2C expression in ductal carcinoma was obviously higher than most other types of breast cancer suggested that UBE2C could be used as a potential marker for distinguishing ductal carcinoma from other types of breast cancers." (PMID 29021715, 2017). "In addition, we compared UBE2C expression in ductal carcinoma and other types of breast cancer." (PMID 29021715, 2017). "Suppression of UBE2C may be a potential therapy target in breast cancer." (PMID 24699941, 2014). "UBE2C knockdown downregulated the expression of TOP2A and treatment with MG132 recovered the expression of TOP2A in breast cancer cells." (PMID 40729680, 2025). "Ubiquitin-conjugating enzyme E2C (UBE2C) belongs to the E2 family and is upregulated in many types of tumors, such as ovarian cancer, breast cancer, pancreatic cancer and glioma, where it serves as an oncogene [6‒9]." (PMID 38634120, 2024). "Compared with PR+ breast cancer, the mRNA levels of UBE2S and UBE2C were higher, while NUMB was lower in PR− breast cancer." (PMID 36860312, 2023). "Compared with ER+ breast cancer, the mRNA levels of UBE2S and UBE2C were higher, while NUMB was reduced in ER− breast cancer." (PMID 36860312, 2023). "Compared with ER+ breast cancer cell lines, ER− cells demonstrated higher UBE2S and UBE2C alongside lower Numb, also in line with transcriptomic results." (PMID 36860312, 2023). "In a paired analysis of breast cancer and adjacent normal tissue, higher levels of UBE2S and UBE2C and lower Numb expression were found in the former." (PMID 36860312, 2023). "Increased expression of UBE2S and UBE2C predicted worse OS and RFS, while increased Numb expression was related to a better outcome in ER+ breast cancer patients." (PMID 36860312, 2023).
breast carcinoma (continued). "UBE2C exerts oncogenic effects on various human solid cancers such as HCC, breast cancer, nasopharyngeal carcinoma, and colon cancer." (PMID 36765811, 2023). "In breast cancer, it has been reported that inhibition of UBE2S or UBE2C suppressed the malignant characteristics of breast cancer cells and sensitized cancer cells to radiation or drugs to enhance clinical effectiveness." (PMID 36860312, 2023). "To validate and characterize the role of UBE2C in the context of brain metastatic disease we used two cancer cell lines, MDA (breast cancer) and A549 (lung cancer)." (PMID 37215954, 2023). "We found that higher levels of UBE2S and UBE2C and lower expression of Numb were correlated with shorter overall survival (OS) and relapse-free survival (RFS) in breast cancer patients." (PMID 36860312, 2023). "After further validation through survival analysis and expression evaluation, CHEK1 and UBE2C were finally identified as hub genes related to the progression of BRCA, especially the luminal A breast cancer subtype." (PMID 35903365, 2022). "This study aimed to determine the prognostic value of UBE2C in invasive breast cancer (BC)." (PMID 35124721, 2022). "UBE2T, UBE2C, and BIRC5 amplifications predicted a worse survival and poor response to therapy across different intrinsic subtypes of breast cancer." (PMID 33671201, 2021). "CDC20, TOP2A, RRM2, and UBE2C were highly expressed not only in HCC, but also in breast cancer and other tumors." (PMID 34568357, 2021). "Recently, UBE2C was mainly studied in gastric cancer, non-small cell lung cancer (NSCLC), breast cancer and colorectal cancer." (PMID 31942195, 2020). "UBE2C is highly expressed in breast microcalcification lesions and its overexpression is correlated with relapse in early HR+/HER2− breast cancer patients." (PMID 32899896, 2020). "As reported, ubiquitin-conjugating enzyme E2C (UBE2C), belonging to the E2 ubiquitin-conjugating enzyme family, plays crucial roles in a variety of malignancies, namely breast cancer, colorectal cancer, melanoma, and hepatocellular carcinoma." (PMID 33186389, 2020). "UBE2C is a key regulator of cell cycle progression in various types of cancers, such as NSCLC, gastric cancer and breast cancer." (PMID 32899896, 2020). "The results indicate that high UBE2C expression has an unfavorable impact on DFS, DMFS, and OS only in patients with HR+/HER2– pN0 and pN1 breast cancer." (PMID 32039034, 2019). "Because tamoxifen downregulated UBE2C expression in MCF-7 cells, we examined the effect of estrogen on UBE2C expression in HR+/HER2– breast cancer cells." (PMID 32039034, 2019). "Multivariate analysis of the effect of UBE2C mRNA expression on disease-free survival (DFS), distant metastasis-free survival (DMFS), and overall survival (OS) in patients with HR+/HER2– breast cancer." (PMID 32039034, 2019). "The present findings suggest that UBE2C overexpression is correlated with relapse and promotes estrogen-dependent/independent proliferation in early HR+/HER2– breast cancer." (PMID 32039034, 2019). "In this study, we examined the correlation between UBE2C mRNA expression and clinical outcomes in patients with HR+/HER2– breast cancer." (PMID 32039034, 2019). "These previous studies were based on literature reviews on the importance of UBE2C tumorigenicity as an essential part of the ubiquitin-conjugating enzyme complex, and they used the MCF-7 cell line as a representative breast cancer cell line." (PMID 32039034, 2019). "Quite remarkably, the two genes upregulated in this module (DHCR7 and UBE2C) are two members of the EndoPredict assay, an RT-PCR assay for predicting response to endocrine treatment in ER+/HER2 − breast cancer." (PMID 25886003, 2015). "To this, we analyzed the expression of two of the genes belonging to the 20-gene signature, UBE2C and AURKA, using immunohistochemistry on tissue array samples from human cervical (n = 55) and breast cancer (n = 86)." (PMID 20630075, 2010).
breast carcinoma (continued). "In conclusion, in breast cancer, any new clinical trial testing bortezomib should compare bortezomib in combination (e.g., trastuzumab) vs the single molecule, and should include patients with proteasome high activity, which could be indirectly evaluated by UBE2C IHC staining." (PMID 19513072, 2009). "Additionally, the E3 ubiquitin ligase ubiquitin-conjugating enzyme E2 C (UBE2C) has been shown to ubiquitinate and degrade RyR2 in breast cancer cells, where it inhibits the Wnt/β-catenin signaling pathway." (PMID 39803908, 2025). "Enrichment difference analysis of the genes showing changes after OHT treatment revealed known breast cancer oncogenes such as HDAC3, UBE2C and CPSF7 among the depleted genes and reported breast cancer suppressors such as CSK, SPRED2 and TSC2 among the enriched genes." (PMID 38914552, 2024). "More specifically, the comparison of UBE2S, UBE2C, and Numb mRNA expression across nine independent analyses demonstrated that UBE2S and UBE2C were markedly elevated and Numb was significantly reduced in breast cancer." (PMID 36860312, 2023). "Besides, we resorted to the Oncomine datasets regarding breast cancer and found that there was evidently higher mRNA expression of UBE2S and UBE2C but lower Numb expression in breast cancer samples than their respective normal controls." (PMID 36860312, 2023). "The expression of UBE2S and UBE2C was generally higher and Numb expression was lower in various cancer types than their respective normal controls, especially in breast cancer, although no obvious differential expression of Numb was shown in certain cancers." (PMID 36860312, 2023). "We confirmed that the expression of KIF4A, UBE2C and COL11A1 was distinctly increased in BC specimens compared with normal breast specimens, while the expression of SFRP1, SAA1 and RBP4 was distinctly decreased in breast cancer specimens." (PMID 35646102, 2022). "In addition, overexpression of UBE2C and UBE2T, which are ubiquitin conjugating enzymes, are known for promoting cell proliferation in breast cancer." (PMID 36077657, 2022). "The top differentially expressed genes (unadjusted P ≤ .001) were all upregulated and included KIFC1 (OMIM 603763), FAM83D (OMIM 618380), UBE2C (OMIM 605574), CLDN4 (OMIM 602909), GRB7 (OMIM 601522), and PKMYT1 (OMIM 602474), each of which have previously reported roles in breast cancer progression." (PMID 34714340, 2021). "To examine whether UBE2C regulates the growth of HR+/HER2– breast cancer cells, we used T47D cells: a HR+/HER2– breast cancer cell line with high UBE2C expression level." (PMID 32039034, 2019). "For example, we showed previously that relative expression of proliferation-related and immune response-related genes, i.e., UBE2C, TOP2A, RRM2, FOXM1, MK167, and BTN3A2, provided a prediction value of adjuvant chemotherapy benefit for patients with ER+/HER2− early breast cancer." (PMID 31779659, 2019). "This suggests that tamoxifen treatment combined with inhibitors targeting UBE2C could be an effective strategy to increase the inhibitory effect of tamoxifen and overcome resistance in HR+/HER2– breast cancer." (PMID 32039034, 2019). "Loss of UBE2C expression markedly decreased cell proliferation by affecting cell cycle progression under estrogen exposure conditions compared with UBE2C knockdown cells without estrogen exposure in HR+/HER2– breast cancer cells." (PMID 32039034, 2019). "The results of univariate and multivariate analyses showed that high UBE2C mRNA expression was strongly associated with poor DFS, DMFS, and OS only in patients with HR+/HER2– pN0 and pN1 (early) breast cancer but not in those with pN2/N3 (late) breast cancer." (PMID 32039034, 2019). "The results of univariate analysis showed that UBE2C mRNA expression as a continuous variable is statistically significantly associated with DFS, DMFS, and OS in only patients with HR+/HER2– breast cancer regardless of LN negativity or positivity." (PMID 32039034, 2019).
breast carcinoma (continued). "However, UBE2C mRNA expression was lower in pN0 and pN1 tumors from HR+/HER2– breast cancer patients than in tumors from other subtype patients." (PMID 32039034, 2019). "Besides, HECTD3, PSMB10, UBD, UBE2C, and UBE2S involved in the ubiquitin proteasome pathway, as well as CCL2, CCR1, CXCL10, CXCL11, and IL2RG implicated in the cytokine–cytokine receptor interaction pathway, might be used for evaluating the efficacy of neoadjuvant chemotherapy in breast cancer." (PMID 29685151, 2018). "These suggested that HECTD3, PSMB10, UBD, UBE2C, and UBE2S might also affect the efficacy of neoadjuvant chemotherapy in breast cancer through the ubiquitin proteasome pathway." (PMID 29685151, 2018). "There was also a difference between UBE2C expression in different molecular subtypes of breast cancer, among which the positive rate of UBE2C expression in HER2-overexpression BRCA was the highest, while the positive expression rate of UBE2C was the lowest in Luminal A BRCA." (PMID 29021715, 2017). "However, the interaction between UBE2S/UBE2C and Numb and their roles in the clinical outcome of breast cancer (BC) are not widely elucidated." (PMID 36860312, 2023). "To explore the expression and potential clinical significance of UBE2S, UBE2C, and Numb in breast cancer, first we analyzed the Oncomine microarray datasets to determine the mRNA levels of UBE2S, UBE2C, and Numb in a variety of malignant tumor types, including breast cancer." (PMID 36860312, 2023). "Consistently, we found out that the copy numbers of UBE2S and UBE2C were significantly upregulated in breast cancer cell lines and rank relatively high among various cancer cell types through CCLE analysis, while the Numb copy number was relatively low in breast cancer cell lines." (PMID 36860312, 2023). "Our data suggest that UBE2C may be a candidate marker for diagnosis of nonpalpable breast lesions but not benign or malignant breast tumors." (PMID 24699941, 2014). "We can therefore hypothesise, first, that poor prognosis in N+ breast cancer is related in a large part to a high activity of the UPS, itself related to tumour high proliferative metabolism, and second, that UBE2C might be considered as a marker of proteasome activity." (PMID 19513072, 2009). "However, univariate, Kaplan–Meier, and multivariate analyses of subgroups according to LN status revealed that high UBE2C expression was associated with significantly shorter DFS, DMFS, and OS in breast cancer with pN0 and pN1 tumors but not in pN2/N3 tumors (P < 0.05)." (PMID 32039034, 2019). "Previous studies suggested that UBE2C expression was accompanied by that of other biomarkers such as AZGP-1, prolactin-inducible protein, and S100A8 or with pituitary tumor-transforming 1 (PTTG1), Survivin and thymidin kinase 1, which might improve outcome prediction in breast cancer." (PMID 24699941, 2014). "We found that breast cancer tissues with medium or high protein staining of UBE2S and UBE2C had negative or weak staining of Numb protein (Cases 1–3>), whereas the lower protein levels of UBE2S and UBE2C displayed strong staining of Numb protein (Case 4)." (PMID 36860312, 2023). "Apart from ER+ and ER− breast cancers, we also compared the expression of UBE2S, UBE2C, and Numb in PR positive (PR+) and PR negative (PR−) breast cancers as well as in HER2 positive (HER2+) and HER2 negative (HER2−) breast cancers." (PMID 36860312, 2023). "Although the expression of UBE2C was only measured at the mRNA level and not at the protein level, we further assessed the clinical significance of UBE2C overexpression in HR+/HER2– breast cancer." (PMID 32039034, 2019). "For example, overexpression of ubiquitin-conjugating enzyme E2C (UBE2C) has recently been thought to play a role in not only NSCLC, but also gastric, colorectal, and breast cancers." (PMID 29761043, 2018). "However, no statistical significance of UBE2S, UBE2C, or Numb expression was observed between HER2+ and HER2− breast cancer." (PMID 36860312, 2023).